CCND1 (cyclin D1)
Diseases named in the same sentence as CCND1 in open-access papers (continued):
Sharing a sentence is not in itself a finding about the gene and the disease.
osteosarcoma (continued). "Knockdown of IL-13Rα2 reduced protein and mRNA levels of cyclin D1, snail, TGF-β, and BCL2, while increasing BAX expression in osteosarcoma cells." (PMID 39598436, 2024). "Therefore, targeting the CCND1 gene may aid in halting Osteosarcoma development." (PMID 37081847, 2023). "This phenomenon did not appear to be specific to RPE cells, as we observed that etoposide treatment induced a G1‐like senescent state (high cyclin D1, low cyclin A and four copies of DNA) both in MCF10A and osteosarcoma (U‐2 OS) cells as well (Fig EV4)." (PMID 36161508, 2022). "KLF8 is a dual transcription factor and can either suppress or activate the transcription of target genes, including cyclin D1, KLF4 and E-cadherin, which are related to tumor development in diverse cancer types including osteosarcoma." (PMID 33817271, 2020). "Cyclin D1 and CDK4 have also been reported to be overexpressed in osteosarcoma and related to its occurrence and development." (PMID 33321940, 2020). "In osteosarcoma, NNT-AS1 can sponge miR-320a and up-regulate the expression of β-catenin, RUNX2, p-AKT, insulin-like growth factor type 1 receptor (IGF1R), MYC, cyclin D1, and MMP-13, thereby promoting osteosarcoma cell growth and tumor development." (PMID 33113895, 2020). "PSMC2 likely drives osteosarcoma via its regulation of cancer-related genes, including ITGA6, FN1, CCND1, CCNE2 and TGFβR210." (PMID 31598166, 2019). "To investigate the underlying molecular mechanism of baicalein on cell cycle regulation, we examined the expression levels of Cyclin D1, Cyclin E1, CDK4, CDK6, c-myc, pRb, p21 and p27 in osteosarcoma cells, which treated with different doses of baicalein." (PMID 29156780, 2017). "Specifically, PVT1 negatively regulated miR-195 in osteosarcoma cells, and silencing PVT1 by siRNA suppressed BCL2, CCND1, and FASN protein expression via miR-195 in osteosarcoma cells." (PMID 27813492, 2016). "PVT1 consequently inhibits the apoptosis of osteosarcoma cells via miR-195/BCL2, induces cell-cycle arrest in osteosarcoma cells via miR-195/CCND1, and promotes the migration and invasion of osteosarcoma cells via miR-195/FASN." (PMID 27813492, 2016). "Subsequent studies showed that the combination of thiram and HC further inhibited the proliferation and migration of osteosarcoma cells, increased apoptosis and cycle arrest, and further decreased the expression of beta-catenin, c-MYC, Cyclin-D1 and MMP7 compared with HC alone." (PMID 36978114, 2023). "The Akt pathway is related to the expression of cyclin D1 and CDK6 in osteosarcoma." (PMID 38130464, 2023). "Transfection of miR-342-5p did not significantly downregulate the expression of the cyclin D1 protein in any of the three osteosarcoma cell lines." (PMID 35337159, 2022). "CCND1 mRNA is a validated target of miR-342-5p in neuroblastomas, but as in chondrosarcoma cell lines, we did not observe downregulated cyclin D1 expression in any of the three osteosarcoma cell lines." (PMID 35337159, 2022). "We did not observe the inhibition of cyclin D1 protein expression by miR-491-5p in the three osteosarcoma cell lines." (PMID 35337159, 2022). "BAMBI has also been reported to regulate cyclin D1, CDK2, and CDK6 in human osteosarcoma cells." (PMID 36109807, 2022). "In this study, it was found that PNS could facilitate p27 expression while suppressing the expression of cyclin D1 and CDK2, so as to arrest osteosarcoma cells in the G0/G1 phase." (PMID 34659528, 2021).
osteosarcoma (continued). "The inhibitory effects of ML264 on osteosarcoma cells are likely mediated via inhibition of JAK2 and STAT3 phosphorylation, decrease in β‐catenin and Runx2 levels, down‐regulation of cyclin D1, cyclin E1, CDK4, N‐cadherin, vimentin, Snail and MMPs expression, and up‐regulation of E‐cadherin levels." (PMID 32285603, 2020). "Furthermore, CEP55 was shown to activate CCND1 and FN1 via the AKT signaling pathway, thereby regulating the proliferation and invasion of osteosarcoma cells." (PMID 32149111, 2020). "In the present study, we found downregulation of Wnt canonical target Cyclin D1 and Survivin in both 143B and SJSA-1 cells after treatment with PRI-724, suggesting that PRI-724 acts in a Wnt-dependent manner in the context of osteosarcoma." (PMID 30613366, 2018). "Moreover, silencing PVT1 by siRNA inhibited BCL2, CCND1, and FASN protein expression via miR-195 in osteosarcoma cells, and BCL2 inhibited the si-PVT1#1-induced apoptosis of U2OS cells." (PMID 27813492, 2016). "PVT1 increased the expression levels of BCL2, CCND1 and FASN by inhibiting miR-195 in osteosarcoma." (PMID 27813492, 2016). "In cancer cells, in addition to the osteosarcoma U2OS cells, DOAY and other p16-defective medulloblastoma cells also showed undetectable or very low levels of cyclin D1 (data not shown), which further supports this link between p16 and cyclin D1." (PMID 21799732, 2011). "We found that silencing LPAATβ expression in osteosarcoma cells resulted in decreased expression of c-Myc, cyclin D1, c-Fos, and MDM2, but an increased Rb expression (data not shown)." (PMID 21152068, 2010). "The expression of LINC01296 was found to be heightened in osteosarcoma (OS) cells and tissues, and there existed a positive correlation between the knockdown or overexpression of cyclin D1 and the expression of LINC01296, indicating LINC01296 to exert a carcinogenic effect on OS through cyclin D1." (PMID 39901673, 2025). "Thus, other signaling pathways could be activated in osteosarcoma cells and counterbalance cell cycle inhibition observed in the presence of ICG-001, such as activation of cyclin D1 gene transcription by Jun/Fos or STAT3 factors." (PMID 34062831, 2021). "Therefore, our current study found that lnc-KASRT promoted osteosarcoma cell viability and mobility; moreover, lnc-KASRT regulated KLF6 alternative splicing to induce KLF6-SV1 while repressing KLF6-WT and regulating P21 and CCND1 expression in osteosarcoma." (PMID 34568030, 2021). "Although Antxr1 knockdown was reported to reduce Ccnd1 and to increase Cdkn1a and Cdkn1b expression in osteosarcoma cells, their expression was not changed in the limb cartilage of Antxr1 tg mice compared with that in wild-type mice at E15.5 by microarray analysis (data not shown)." (PMID 32244499, 2020). "Thus, the protein levels of total GSK 3β, phosphorylated GSK 3βser9, nuclear β-catenin, and cyclin D1, which are the key signaling molecules in the Wnt signaling pathway, were measured in HOS and MG63 osteosarcoma cells transfected with siRNA1-URG4, siRNA2-URG4, NC, and blank by WB." (PMID 32552851, 2020). "This indicated that TEM8-ERK1/2-cyclin D1 was not the only mechanism which could modulate the proliferation of osteosarcoma." (PMID 26996335, 2016). "Induction of SASH1 expression reduced cyclin D1 and matrix metalloprotease- (MMP-) 9 expression and increased caspase 3 expression, which suggested that overexpression of SASH1 in human osteosarcoma MG-63 cells might inhibit cell growth, proliferation, and invasion and promote apoptosis." (PMID 26424902, 2015).
osteosarcoma (continued). "β-catenin protein expression was detected in the membrane and cytoplasm of 69.6% (32/46) of the osteosarcomas, negative c-myc protein expression was recorded for 52.2% (24/46) of osteosarcomas and negative cyclin D1 protein expression was recorded for 47.8% (22/46) of osteosarcomas." (PMID 24942472, 2014). "Western blots showed that 24 h DFO and DFX treatment markedly decreased the expression of cyclin D1 and cyclin-dependent kinase 4 (CDK4) in osteosarcoma cells, but CDK4 expression not significantly decreased in K7M2 cell." (PMID 34281233, 2021).
breast tumors (104 papers, 1996 to 2025). "For instance, very recently, it is reported that in breast tumors inhibition of important cellular energy sensor such as mTOR Complex (TORC) 1/2 causes a decrease of Cyclin D1 protein, RB phosphorylation and E2F-mediated transcription." (PMID 33317149, 2020). "We show that increased expression of cyclin D1 in stromal fibroblasts can transform it to a cancer-associated fibroblast phenotype and that stromal cyclin D1 is sufficient to augment breast tumor epithelial cell growth in mice." (PMID 29137220, 2017). "Reports demonstrate that CcnD1 protein is an oncogenic driver, upregulated in up to 50% of breast tumors and associates with reduced patient survival and resistance to chemotherapeutics." (PMID 24658335, 2014). "CCND1 amplified breast tumours have been reported to display loss of the distal part of 11q in 70% of cases." (PMID 24559095, 2014). "Amplification, mutation, and high expression of cyclin D1 are reported to be associated with resistance to chemotherapy and poor prognosis in breast tumors, brain tumors and testicular germ cell tumors." (PMID 23806108, 2013). "The CCND1 gene encoding cyclin D1 at 11q13 is amplified in 30–40% of breast tumors, and its product is the rate-limiting factor for cell cycle progression." (PMID 23565238, 2013). "In contrast, the luminal subtypes of BRCA2 mutated breast tumors were associated with high expression of cyclin-D1 gene products (χ2; P = 0.005)." (PMID 21958427, 2011). "A meta-analysis of primary breast tumours revealed significant associations between CCND1, ID1, CDH1 (E-cadherin) and recurrence-free survival." (PMID 21955753, 2011). "However, is CCND1 overexpression a cause or a consequence of transcriptional activation of oestrogen receptors in breast tumour cells?" (PMID 11870541, 2002). "The vast majority of breast tumors bearing CCND1 amplification are readily defined as ER positive, are luminal B by gene expression analysis, and overexpress cyclin D1 protein; most notably, patients with CCND1 amplified tumors show reduced survival times and associations to treatment resistance." (PMID 22924091, 2012). "Compared with that in control cells, the half‐life of the CCND1 mRNA in DDX5‐overexpressing breast tumor cells was prolonged." (PMID 41263459, 2025). "Given the high expression of the CCND1 mRNA in breast tumor cells, a consideration of other proteins that bind to this stem–loop structure for mRNA stabilization is reasonable." (PMID 41263459, 2025). "In this study, we discovered that the RBPs ZC3H12D and DDX5 (DEAD‐box helicase 5) antagonistically regulate CCND1 mRNA stability and expression in breast tumor cells." (PMID 41263459, 2025). "Overexpression of DDX5 can attenuate ZC3H12D‐induced suppression of CCND1 mRNA in breast tumor cells." (PMID 41263459, 2025). "In fact, cyclin D1 expression has been proposed to be a biomarker post treatment with ONC201 for breast tumors." (PMID 40305155, 2025). "Ribosomal protein L4 (RPL4) was shown to interact with ZC3H12D and facilitate the degradation of the CCND1 mRNA in breast tumor cells." (PMID 41263459, 2025). "We subsequently analyzed the effects of ZC3H12D and DDX5 on CCND1 mRNA expression in human breast tumors." (PMID 41263459, 2025). "The IND enabling experiments, in which cyclin D1 anti-sense inactivation reduced breast tumor growth, led to the rationale development of therapies targeting the cyclin D1 holoenzyme." (PMID 40565165, 2025). "Studies have shown that high expression of cyclin D1 in head and neck, colorectal, esophageal and breast tumors have been considered to be a characteristic of poorer prognosis, thus becoming a potential biomarker." (PMID 38742684, 2024). "TACSTD2-low breast tumors were enriched for copy number amplifications in CCND1 and FGF/R family member genes." (PMID 38986529, 2024).
breast tumors (continued). "Gene expression analysis obtained from the METABRIC database suggests that aggressive breast tumours also display an increase in expression not only for Cyclin D1 and E2F, but also for the WNT signalling pathway (relative enrichment of WNT pathway=1.75)." (PMID 38678032, 2024). "Considering that a significant number of ER+ breast tumors initially respond to tamoxifen therapy but eventually develop resistance through various mechanism, including the overexpression of cyclin D1, our findings carry significant clinical relevance." (PMID 38004441, 2023). "In 20% of human breast malignancies, cyclin D1 gene is amplified cyclin D1 protein is produced at a high level in 50% of human breast tumors." (PMID 36476410, 2022). "In this line, we detect DDR2 overexpression in metastatic BC patients with CCND1 gene amplification, a worse survival predictive biomarker in breast tumors." (PMID 35711892, 2022). "In breast tumor tissues of the curcumin-treated group, a significant suppression of NF-κB p65 and a deregulation of NF-κB-related genes expression, cyclin D1, and PECAM-1 were detected." (PMID 34298639, 2021). "An additional study suggested overexpression of cyclin D1 gene in the ER-positive MCF-7 breast tumor cell line, which was responsible for hyperproliferation undergrowth factor-deprived conditions." (PMID 33920506, 2021). "Cyclin D1 is probably the most extensively studied cyclin in breast tumors, and its overexpression has been reported in more than 50% of breast cancer cases, as detected in TNBC and hormone-independent HER2+." (PMID 34298639, 2021). "An abnormal expression of cyclin D1 was displayed in 66% of mammary infiltrating duct carcinomas, suggesting its role in breast tumor metastasis." (PMID 33920506, 2021). "In ER+ve breast tumors, there is an increased expression of Cyclin D1 or CCND1 gene amplification, as well as, p16 or Rb losses." (PMID 33777765, 2021). "In breast tumors, higher Cyclin D1 positive rate corresponds to higher ER positive rate but lower Her-2 positive rate." (PMID 33317149, 2020). "We recentlyinvestigated the copy number status of the genes FOSL1,GSTP1 and CCND1 in primary breast tumors withlymph node metastasis (Callegari etal., 2016)." (PMID 30816904, 2019). "Expression of both cyclin D1 and c-Myc genes is required for estradiol-mediated proliferation in breast tumors." (PMID 30736340, 2019). "Further extending these data, the current results demonstrate that 3MC engages GPER toward the up-regulation of both CYP1B1 and the cell-cycle regulator cyclin D1 in breast tumor cells and major components of the cancer stroma as CAFs." (PMID 31370872, 2019). "RANK signaling stimulates proliferation and survival of breast tumor cells through induction of cyclin D1 and Bcl-2 protein expression." (PMID 31796128, 2019). "CCND1 has been shown to be amplified in a large number of breast tumors and as a key regulator of the G1/S cell cycle transition, promotes tumor cell proliferation and metastasis." (PMID 30325954, 2018). "Increased cyclin D1 gene copy number is found in up to 20% of breast tumors suggesting that activation of cyclin D1 can occur via additional mechanisms, including transcriptional and post-transcriptional dysregulation." (PMID 29137220, 2017). "Altogether these results suggest that Cyclin D1 is an important CtBP1 target modulated in the mammary gland and in breast tumor by MeS." (PMID 26933806, 2016). "To do so, we had to deal with the fact that CCND1 in lung and breast tumour cell lines, EZR (Ezrin) and HMGB1 in normal Schwann cells, were the only published nuclear targets of ErbB3." (PMID 27191720, 2016).
breast tumors (continued). "Cyclin D1 is overexpressed in the majority of human breast tumors, many of these representing downstream effects through induction of cyclin D1 by oncogenic signals (Ras, MAPK), Src, ErbB2, STATs, Notch, NFκB." (PMID 25940700, 2015). "Fluorescent in-situ hybridization was performed on a tissue microarray of 495 breast tumors (74% of patients) to measure CCND1 and RSF1 copy number." (PMID 24367492, 2013). "Cyclin D1 is a member of the cyclin family of cell cycle regulators, and its overexpression favors more rapid and sustained proliferation of breast tumor cells." (PMID 24367492, 2013). "We validated the methodology on a breast tumor for which array comparative genomic hybridization (CGH) had shown focal amplification of CCND1." (PMID 24367492, 2013). "In the current study, we found that transfection with a precursor of miR-16 (pre-miR-16) resulted in the inhibition of MPA-induced cyclin D1 expression in C4HD cells, indicating that cyclin D1 is also a downstream target of miR-16 in breast tumor cells." (PMID 22583478, 2012). "The CCND1 gene is amplified in up to 15 % of breast tumors, with overexpression of its corresponding protein found in up to 50 % of cases." (PMID 22924091, 2012). "If these strategies are rigorously applied, they will solidify the importance of CCND1 amplification as a clinical marker and will allow us to determine the relevance of aberrant cyclin D1 protein expression in breast tumors." (PMID 22924091, 2012). "The observed inverse correlation between the levels of two cluster members, miR-17-5p/20a and cyclin D1, in human breast tumors led to the identification of miR-17-5p/20a as a translational suppressor of cyclin D1 mRNA via binding to its 3' UTR." (PMID 21314915, 2011). "Cyclin D1 is over-expressed in most breast tumor cell lines through over-expression and/or amplification at its genomic locus, 11q13." (PMID 21935420, 2011). "MiR-96 expression and cyclin D1 mRNA expression were markedly upregulated, but the expression levels of p27Kip1 mRNA and FOXO3a protein were downregulated in breast tumors tissues as compared with those in normal human breast tissues." (PMID 21203424, 2010). "Our results demonstrate that mammary gland targeted cortactin did not affect mammary epithelial cell morphology and did not provide proliferative advantages in the development of (pre-malignant) breast tumor in either WT or MMTV-cyclin D1 transgenic mice." (PMID 16536875, 2006). "In this regard, we recently suggested in a small series of breast tumors (n=33) that CCND1 mRNA overexpression is related to oestrogen receptor positively." (PMID 11870541, 2002). "We used real-time quantitative PCR and RT–PCR assays based on fluorescent TaqMan methodology to quantify CCND1 gene amplification and expression in a large series of breast tumours." (PMID 11870541, 2002). "Among the 10 patients in whom both the primary breast tumour and matched normal breast tissue were investigated, CCND1 expression was far higher in three tumours than in the normal tissue (NCCND1=8.1, 4.8 and 3.6, compared to 0.9, 1.2 and 0.2, respectively)." (PMID 11870541, 2002). "CCND1 overexpression was observed in 44 (32.8%) of 134 breast tumour RNAs, ranging from 3.3 to 43.7 times the level in normal breast tissues, and correlated significantly with positive oestrogen receptor status (P=0.0003)." (PMID 11870541, 2002). "However, the mechanism controlling the expression of the CCND1 gene in breast tumor cells is still not fully understood." (PMID 41263459, 2025). "We further examined the effect of DDX5 on CCND1 mRNA expression in breast tumor cells." (PMID 41263459, 2025). "Moreover, the expression of CCND1 in human breast tumor tissues decreased with increasing ZC3H12D expression but increased with increasing DDX5 expression." (PMID 41263459, 2025).